CXCR4 (C-X-C motif chemokine receptor 4)
Diseases named in the same sentence as CXCR4 in open-access papers (continued):
Sharing a sentence is not in itself a finding about the gene and the disease.
tumor (continued). "In sum, our findings strongly suggest a relevant cooperation between CXCR4/ACKR3 and growth factor receptors in tumor progression, likely facilitated by the simultaneous increased abundance/functionality of these proteins in many tumor types." (PMID 36233192, 2022). "In gastric cancer cells, CXCL12/CXCR4 signaling can activate NF-kB; this upregulates the expression of serine protease inhibitor branch B member 3 (SERPINB3), thus promoting the metastasis of tumor cells." (PMID 35893797, 2022). "Among these molecules, CXCR4 and SELPLG play a key role in the tumor-tropic processes of MSCs." (PMID 35463812, 2022). "CTCE-9908 inhibits tumor cell invasion and tumor angiogenesis via the CXCL12/CXCR4 axis." (PMID 35893797, 2022). "All the data presented so far underscore the role that CXCR4 and CD47 play in tumor promotion." (PMID 36293358, 2022). "Furthermore, the percentage of positive tumor cells across all the markers was higher within hypoxic regions compared to normoxic regions in SCC patients, but only CXCR4 in the R cohort was statistically significant (p = 0.04)." (PMID 35993091, 2022). "Therefore, to improve the sensitivity of tracers for tumor imaging, we used a polyvalent strategy to develop a heterodimeric tracer, 68Ga-yG5-RGD, which targeted CXCR4 and integrin αvβ3 simultaneously for PC imaging." (PMID 36145541, 2022). "Surprisingly, treatment with a triple combination of VIP-R antagonist, anti-PD-1 and a CXCR4 antagonist resulted in similar tumor growth rates and survival to control mice receiving no drugs." (PMID 36302761, 2022). "Indeed, it is now well known that selective inhibition of BTK (or PI3Kdelta) within the BCR (or CXCR4) pathways leads to peripheral lymphocytosis by disrupting the interaction between the TME and tumor B cell and their homing." (PMID 35804999, 2022). "Previous results from our group, showed that NSCLC stem cells, the CD133+/CXCR4+EpCAM subset, was triggered by EMT, an event that can be induced by stimuli from the tumor microenvironment, able to convert progenitor cells into cancer stem cells, endowed with invasiveness ability." (PMID 35563517, 2022). "Due to CXCR4 antagonism and miR-210/KRASG12D downregulation, such nanoparticles with triple-actions favorably modulated desmoplastic tumor microenvironment and thus promoted the infiltration of cytotoxic T cells into tumor tissues." (PMID 35875197, 2022). "The anti-CXCR4 antibody blocking of the CXCL12/CXCR4 axis was found to significantly reduce TEMs, but not Tie-2– TAMs, recruitment to combretastatin-A4-phosphate (the vascular-disrupting agent)-treated tumour in a murine model." (PMID 36497114, 2022). "In a study in which human PC specimens were harvested and analyzed by organotypic slice culture to test the effects of the combination of anti-PD-1 (20 mg/mL) and CXCR4 inhibitor AMD3100 (100 mg/mL), CD8+ T cell migration and induction of tumor cell apoptosis were observed." (PMID 35139879, 2022). "Furthermore, several chemokine signaling axes also contribute to tumor vasculature generation such as CXCLs/CXCR2, SDF1/CXCR4, and CCL2/CCR2 axis directly or indirectly." (PMID 36324128, 2022). "As expected, no variation in primary tumor volume was observed between the control and nanotoxin-treated animals, as the CXCR4 expression within the tumor tissue was negligible." (PMID 35456719, 2022). "Indeed, co-treatment of a CXCR4 inhibitor (AMD3100) with ICB in PDAC mice with an intact FAP+ CAFs population induced rapid T cell accumulation and significant tumor regression." (PMID 36671452, 2022).
tumor (continued). "Ten chemokine receptors (CXCR1, CXCR2, CXCR4, CXCR6, CCR3, CCR6, ACKR4/CCRL1, CCLR2, CX3CR1, and ACKR1/DARC) were identified as differentially expressed from the DEG analysis between Black, White and Asian patient normal and tumor samples." (PMID 35754051, 2022). "To date, the vast majority of oncology studies evaluate the clinical efficacy of CXCR4 antagonists based on their prominent anti-tumor or mobilizing effects and not anti-vasculogenesis effects." (PMID 36568151, 2022). "Like CXCR4, CXCR7 can mediate various cancer processes, including tumor growth and metastasis." (PMID 36118530, 2022). "EPCs lead to tumor progression through increasing production of VEGF-A, CXCL12, or CXCR4." (PMID 35203510, 2022). "Another CXCR4 antagonist, BL-8040 (Motixafortide), in combination with programmed death 1 (PD-1, also known as CD279) antagonist pembrolizumab increases CD8+ T cell tumor infiltration and decreases tumor cell density (COMBAT trial, NCT02826486)." (PMID 35159011, 2022). "Regarding the CXCR4-targeted nanocarrier, 60% accumulated in the SC tumor; therefore, selectively targeting CXCR4+ cancer cells, without toxicity in non-tumor organs." (PMID 35884987, 2022). "At present, some researchers have confirmed that after PC saponin administration, serum IL-6 and TNF-α levels, expression of VEGF and CD31 in liver tissues, and CXCR4, CXCL12, MMP-9 and MMP-2 proteins in spleen tumor tissues of colon cancer mice were significantly reduced." (PMID 35814470, 2022). "We further transfected SK-Hep1 cell lines with CXCR4 plasmid to determine whether tumor-derived DNA and the effect of sinine hydrochloride on HCC cells were related to the CXCL12-CXCR4 chemokine axis." (PMID 35860597, 2022). "The newly synthesized CXCR4 antagonist, PRX177561, significantly attenuates GBM tumour growth and might augment the effects of antitumour chemotherapy and RT." (PMID 36140541, 2022). "Interestingly, in the splenic CD205+G‐MDSC from 4T1 and 4T07 tumor‐bearing mice, the MFI of CXCR4 significantly decreased after 48‐hr fasting; In contrast, CD205+ G‐MDSCs from bone marrow expressed increased levels of CXCR4." (PMID 34646521, 2021). "Though CXCR4 affinity was low for these compounds, the radiotracers [18F]RPS-534 (26, RPS-534, IC50 218 ± 38 nM) and [18F]RPS-547 (27 ̧ RPS-547, IC50 601 ±118 nM) displayed good tumor-to-blood, tumor-to-muscle, and tumor-to-lung uptake ratios in PC3-CXCR4 xenograft tumors." (PMID 34500609, 2021). "A study using selective ACKR3 modulators emphasized the involvement of ACKR3 in GSC growth in vitro together with CXCR4, although this report revealed that GSC tumor formation in vivo was independent of CXCR4 or ACKR3 activity." (PMID 35008294, 2021). "In addition, CXCR4 and its ligand CXCL12 have been demonstrated to facilitate the accumulation of MDSC at the tumor site in different tumor models." (PMID 33578808, 2021). "Moreover, inhibition of the CXCL12/CXCR4 signaling axis with AMD3100 (a CXCL12/CXCR4 antagonist) weakened the tumor’s mesenchymal signature in the SVZ and increased the tumor’s sensitivity to radiotherapy." (PMID 34359668, 2021). "Furthermore, increased CXCL12 concentration in the TME activates the CXCL12/CXCR4 axis and enhances the recruitment of EPCs to HCC, which also promotes tumor neovascularization." (PMID 34386499, 2021). "The positive correlation between HOXB5 expression and its target genes CXCR4 and ITGB3 in human CRC cell lines led us to explore whether it also existed in primary tumor tissues." (PMID 33456563, 2021). "CXCR4 and CXCR7 are expressed individually or together, depending on the tumor type." (PMID 34298991, 2021). "Looking into detail in each of these categories, genes previously related to bone tropism were found to be overexpressed in PC3-BM cells, such as CXCR4 and its ligand CSF1, as well as CCL2, all of them directly involved in signaling pathways regulating circulating tumor cells (CTCs) homing to bone." (PMID 34944822, 2021).
tumor (continued). "Strikingly, we found that a significant CXCR4 and CCR7 association was only detected in cells from the advanced primary tumours, whereas receptor interaction was practically absent in tumour cells from hyperplasia and early tumour stages." (PMID 34685420, 2021). "Its effects are mediated by CXCR4 and CXCR7 receptors on tumor cells." (PMID 34212564, 2021). "In the context of PDAC, our group has demonstrated that low-dose PDT followed by chemotherapy significantly reduces stem-like tumor cell populations that are known to contribute to treatment resistance and metastatic potential, in part through the downregulation of CD44 and CXCR4." (PMID 34830934, 2021). "In conclusion, we have unveiled a previously unknown activity of CXCR4, which by co‐internalizing CD47 exposes tumor cells to immunosurveillance." (PMID 33956406, 2021). "Indeed, senescent tumor cells exhibit high invasion ability and have an improved survival via CXCL12/CXCR4 signaling." (PMID 33954107, 2021). "Compared to 2D monolayers, there was a twofold increase in the expression of the stemness-related transcription factors SOX2 and KLF4 in PA-ECM cultures and a much higher proportion of CD133 + /CXCR4 + cells than in spheres or organoids, which falls in the range of matched PDX tumours." (PMID 34561461, 2021). "Targeting the CXCL12-CXCR4 axis by treatment with a specific CXCR4 inhibitor AMD3100, also known as Plerixafor, reverses FAP-positive CAF-mediated immunosuppression, infiltration of CD8+ T cells into the tumor." (PMID 33572223, 2021). "While we observe that some migrated tumor cells highly express CXCR4 other cells do not, we determined a dominant role of AQP1 in the migrating cells in the scratch assay." (PMID 33467498, 2021). "Interestingly, it has recently been reported that combined treatment of novel CXCR4 antagonist with anti-PD-1 determined an increase of T cells/MDSC ratio and reduced tumor growth in the murine model." (PMID 33963011, 2021). "Further, we observe paclitaxel treatment significantly reduces tumor growth in control tumor bearing mice, whereas, failed to do so in CXCR4 overexpression condition in HCT-116 xenograft model." (PMID 33966046, 2021). "The CXCR4 expression of four non-pretreated tumour lesion samples was confirmed immunohistochemically." (PMID 33579381, 2021). "Apart from tumor and endothelial cells, CD4+ T lymphocytes express CXCR4." (PMID 34203660, 2021). "Although the role of CXCR4 is better characterized in the tumor interstitium, the CXCR4/CXCL12 axis is also expressed in the tumor vasculature where it is known to promote angiogenesis and vascularization through induction of VEGF and/or recruitment of endothelial progenitor cells." (PMID 34793563, 2021). "CXCR4 inhibition in combination with anti-VEGF therapies has been tested in animal models with some success, and is another possible therapeutic modality to target angiogenic responses within the tumor microenvironment." (PMID 33391498, 2021). "A CXCR4 antagonist led to decreased tumour-EC contacts in 2 out of 3 primary samples but did not affect viability in the three samples." (PMID 34572836, 2021). "CXCR4 is widely expressed in many tissues and CXCL12/CXCR4 signaling plays an important role in diverse processes such as cell proliferation, survival, and differentiation, as well as inflammatory responses and tumor development." (PMID 33962657, 2021). "For example, FAP-expressing CAF have been shown to exclude T-cells from tumours through secretion of CXCL12; targeting the CXCL12/CXCR4 signalling axis using plerixafor (a CXCR4 inhibitor) has been shown to overcome this exclusion effect and promote response to anti-PD-1." (PMID 35048030, 2021). "Through in vitro evidence, overexpression of CXCR4 has been identified as a negative prognostic factor in many different neoplasms." (PMID 34209026, 2021). "CXCR4 and CCR7 are known to promote tumor metastasis via cell migration and invasion." (PMID 33406809, 2021).
tumor (continued). "Tumor growth correlated inversely with CXCL12 and positively with CXCR4 expression, suggesting that local CXCL12 may impair the primary tumor cell response to the ligand gradient that may contribute to driving the tumor progression." (PMID 34834449, 2021). "PCa and perhaps other neoplasms (e.g., breast) may use the chemokine stromal cell-derived factor-1 (SDF-1 or CXCL1) and its receptor CXCR4 to promote their spreading to the bone and other tissues." (PMID 34247196, 2021). "We inoculated 2 million control or CXCR4 knockdown cells of all three (HT-29, DLD-1 and HCT-116) into the flank of right or left hind leg of 4–6 weeks old nude Crl: CD1-Foxn1nu mice and assessed tumor progression." (PMID 33966046, 2021). "We then used lentiviraus-CXCR-4-shRNA to silence CXCR-4 expression in Cal 27 and HN 30 cell lines and found that pDC-CM-mediated tumor cell proliferation was significantly inhibited in CXCR-4-silenced cells, as reflected by the CCK-8 and colony formation assays." (PMID 33854604, 2021). "Inhibition of CXCR4 by AMD-NPs in combination with either conventional sorafenib treatment or VEGF siRNA induces synergistic anti-angiogenic effects and inhibits local and distant tumor growth in HCC." (PMID 34386499, 2021). "Although there was no observed difference in PAI‐1 expression between shSDC2 and shControl tumours, there was a decrease in CXCR4 expression in shSDC2 tumours, albeit not significant." (PMID 33152121, 2021). "CXCR4 has been shown in this study to be critical to OSCC invasion and metastasis, and has garnered attention in recent years for its role in multiple other tumor types, with overexpression in at least 23 other cancer types." (PMID 33927349, 2021). "However, while CXCR4/CXCL12 regulates the functions of vascular endothelial cells and tumour cells, their influence on NK cell function is still under debate." (PMID 34709764, 2021). "Depending on tumor size we analyzed two to six tissue areas regarding the RNA expression properties with respect to their hypoxia-dependent factors as well as NMYC, NCAM and CXCR4." (PMID 33467498, 2021). "Moreover, rhosin inhibited tumor cell adhesion to the extracellular matrix via suppression of RHAMM expression, and inhibited SDF-1-induced cell migration and invasion by decreasing CXCR4 expression in B16BL6 and 4T1 cells." (PMID 33406809, 2021). "Finally, the TNC retention effect of the CM was abolished with AMD, supporting a role of CXCR4 signaling in CD8 T cell attraction and retention by the secretome from the tumor cells." (PMID 33988305, 2021). "Moreover, IL-6 upregulates the expression of the androgen receptor and of CXCR4 on tumor cells, thereby favoring tumor cell proliferation and recruitment to bone via the CXCL12/CXCR4 axis." (PMID 34064859, 2021). "Although weak to moderate CXCR4 expression could be corroborated by IHC in 10/11 cases, 18F-FDG PET/CT detected significantly more tumor lesions (102 vs. 42; total lesions, n = 107; p < 0.001)." (PMID 33805264, 2021). "Altogether, our results propose that releasing CD8 TIL from the tumor matrix may be an important factor to empower ICT, where targeting matrix‐regulated CXCR4 signaling is worth to be further explored." (PMID 33988305, 2021). "In line with a potentially more “silenced” phenotype, these nonlesional tumor cells harbored elevated levels of CXCR4, CD69, HSPA1A, ZFP36, IL7R and TXNIP when compared to matched lesional skin." (PMID 34583709, 2021). "The role of CXCR4, who functions through combing its cognate chemokine ligand CXCL12 to orchestrate cancer cells directly or through inducing angiogenesis and recruiting immune cells indirectly, is broadly concerned in multiple tumour‐promoting processes." (PMID 34170080, 2021). "Interestingly, TGF-β, which is secreted by tumor cells and tumor-infiltrating regulatory T cells, enhances the expression of chemokine receptors CCR1, CCR3, CCR5, CCR6, and CXCR4 on DCs, thereby driving DC migration to the TME." (PMID 34290401, 2021).
tumor (continued). "Blockage of CXCR4 signaling has been shown to inhibit PCa bone metastasis, but a role of CXCR4 in the communication between osteoclasts and tumor cells is still not clear in PCa." (PMID 33731701, 2021). "Through comparison with the tumor-penetrating [18F]MCFB PET agent, we found that, interestingly, whole-tumor CXCR4 does not necessarily reflect the receptor’s expression in the tumor vasculature." (PMID 34793563, 2021). "Furthermore, in a subcutaneous mouse model of PDAC, CXCR4 blockade by AMD3100 reduced intratumor blood flow and tumor vascular density, supporting that CXCL12 can promote angiogenesis." (PMID 35008248, 2021). "In contrast, EPI-X4 as endogenous antagonist, being not useful as tumor-homing peptide, is highly efficient in suppressing signaling from CXCR4 and in inhibiting CXCL12-induced cancer cell migration in vitro and inflammatory cell infiltration in vivo." (PMID 34208189, 2021). "However, the co-expression of IL-33 and CXCR4 showed a significant correlation with clinical parameters, including TNM stage, nodal involvement, stage, and tumor differentiation." (PMID 34298657, 2021). "A prime example is CXCL12, which together with its receptors CXCR4 and CXCR7 guide tumor cell metastatic migration, recruit stromal cells (including immune cells), promote angio- and lymphogenesis and constitute a crucial part of the CSC niche in many tumor entities." (PMID 33530455, 2021). "Although CXCR4 expression is a prognostic factor for several gastrointestinal tumors, CXCL12–CXCR4/CXCR7 axis appears to act as tumor promoter and not tumor initiator." (PMID 34298991, 2021). "In addition, SOX11 mediates the expression of platelet-derived growth factor alpha (PDGFA), focal adhesion kinase (FAK) and C-X-C motif chemokine receptor 4 (CXCR4), which promote angiogenesis, metastasis and tumor cell migration, respectively." (PMID 34256839, 2021). "We thus speculate that a triple combination of 5-FU + SB43152 and a CXCR4 inhibitor (e.g., AMD070) or L1CAM inhibitor could be an effective therapeutic strategy to eradicate the tumor." (PMID 33897875, 2021). "It is also shown that tumor cells cotreated with TS at 1 μg/ml or TRAIL at 25 ng/ml downregulate the expression of STAT3 target genes (cFLIP, Bcl-xL, ICAM1, VEGF, TRAF1 and the chemokine receptor CXCR4)." (PMID 34543231, 2021). "Nonetheless, the detailed mechanisms of how CXCR4 /CXCL12 interaction stimulates metastasis and/or tumor growth and their complete implications on metastatic lung cancer in bone are unknown." (PMID 36046435, 2021). "High tumor-uptake and low CXCR4 expression in non-tumor regions indicate promising preconditions for a CXCR4 specific radionuclide therapy." (PMID 33579381, 2021). "Importantly, the tumor cells could significantly produce not only the ILs such as IL-6, IL-8, and IL-11, required for osteoclastogenesis, but also strengthen the expression of CXCR4 and CXCR7, establishing a “fertile soil” that accelerates tumor cells to adhere to bone matrix and thrive in bone." (PMID 36046435, 2021). "In support of these studies, CXCR4 upregulation in HNSCC is confined to tumor nests, but not in the stroma." (PMID 33925575, 2021). "Although molecules targeting CXCR4/CXCR7 have been developed for preclinical and clinical studies in cancer, efforts are needed to develop specific and efficient drugs that target both tumor and TME." (PMID 33937018, 2021). "However, the expression of XBP1s, CXCR4, and CD44 was much higher in APVT tumor cells of PCNSL than those in the control tissues, which were negative except for very weak positive for CD44." (PMID 34093792, 2021). "It is now generally accepted that tumour cells are affected by oxygen tension, calcium flux and homing signalling such as SDF-1/CXCR4 and adhesion molecules, all of which mediate shuttling of cancer cells between the niches and between dormant and active states." (PMID 35006432, 2021).